TTR (transthyretin)
Diseases named in the same sentence as TTR in open-access papers (continued):
Sharing a sentence is not in itself a finding about the gene and the disease.
polyneuropathy (continued). "The duration of survival from the time of diagnosis can vary widely, depending on the duration of symptoms prior to diagnosis, TTR genotype, and clinical presentation, with cardiac involvement associated with a poorer prognosis than that for isolated polyneuropathy." (PMID 40433205, 2025). "If a TTR variant can be detected, neurological examination should be performed to screen for polyneuropathy, especially because additional treatment options, like silencer therapies, are available for ATTRv with polyneuropathy." (PMID 39407933, 2024). "Transthyretin amyloidosis (ATTR amyloidosis) is a life-threatening disease caused by the deposition of misfolded transthyretin (TTR) protein amyloid fibrils in various tissues, leading to polyneuropathy and/or cardiomyopathy, among other clinical manifestations." (PMID 39458146, 2024). "Given the scarcity of evidence and data on ATTRv patients and carriers in Spain, this study was performed to describe the clinical profile of AC of pathogenic TTR gene mutations and patients with Coutinho stage 1 ATTRv with polyneuropathy (PN), diagnosed in the last 12 months in Spain." (PMID 39242501, 2024). "Additionally, in the presence of an ATTR-CM-associated polyneuropathy, specific drugs targeting transthyretin can be used." (PMID 38275387, 2023). "There is a notable genotype–phenotype variability, and some specific TTR mutations have historically been associated with particular disease manifestations, with V30M most often associated with predominant polyneuropathy and V122I most often associated with predominant cardiomyopathy." (PMID 34602081, 2021). "Previous studies have shown that patients with hATTR cardiomyopathy have significantly lower TTR levels than patients with wtATTR or hATTR polyneuropathy." (PMID 40722719, 2025). "Deposits of TTR aggregates in the heart and central nervous system can lead to devastating cardiomyopathies and polyneuropathies, respectively." (PMID 40816471, 2025). "After consultation between the cardiologist and neurologist, polyneuropathy was determined to be the dominant disease presentation, so a TTR gene silencer was prescribed to manage disease progression." (PMID 40433205, 2025). "NfL has been demonstrated to increase in patients with acute and chronic demyelinating polyradiculoneuropathy, diabetic polyneuropathy, and with neurogenetic conditions such as hereditary amyloidogenic transthyretin (ATTRv) amyloidosis with polyneuropathy." (PMID 40462552, 2025). "Transthyretin amyloidosis is a disease resulting from accumulation of misfolded proteins from a mutated or wildtype transthyretin (TTR) gene, into harmful amyloid fibril deposits, leading to polyneuropathy and/or cardiomyopathy Ruberg and Berk (2012)." (PMID 41476860, 2025). "The NEURO-TTRansform trial (NCT01737398), an open-label, single-group, phase 3 study, investigated Eplontersen in adults with ATTRv polyneuropathy, NIS 10-130, and a documented TTR variant." (PMID 39044869, 2024). "TTR silencers are approved by the FDA for the treatment of ATTRv polyneuropathy and are currently being tested for the treatment of ATTR-CM." (PMID 39092395, 2024). "Although amyloid deposits composed of mutant TTR are shared by all ATTRv patients, the pathogenesis of polyneuropathy is still unclear." (PMID 38486098, 2024). "This extracellular accumulation of transthyretin-derived amyloid fibrils can lead to various pathological conditions, primarily cardiomyopathy and polyneuropathy." (PMID 39044869, 2024). "ATTRv polyneuropathy emerges due to the accumulation of TTR within the PNS, leading to the development of sensory-motor and autonomic neuropathies characterized by length-dependent patterns." (PMID 39286810, 2024). "In pathological conditions, TTR protein aggregates and stores in tissue and various organs, such as nerves and the heart, inducing progressive and debilitating polyneuropathy and life-threatening cardiomyopathy." (PMID 39796004, 2024).
polyneuropathy (continued). "Both mutant and wild-type transthyretin contribute to the resulting polyneuropathy and cardiomyopathy, leading to significant sensorimotor disturbances and severe cardiac conditions such as heart failure and arrhythmias, thereby impacting quality of life." (PMID 39044869, 2024). "Clinical and in-vivo results conducted on a small group of ATTR patients suffering from polyneuropathy showed a durable inhibition of TTR gene expression ranging from 80%–90% after 28 days of receiving a single dose." (PMID 38047291, 2023). "In 2022, Vutrisiran, a transthyretin-directed small-interfering ribonucleic acid, was approved for the treatment of polyneuropathy induced by hATTR." (PMID 36983602, 2023). "Patients with CIAP who underwent TTR gene sequencing more frequently had painful polyneuropathy (42% vs. 28%, p 0.03), CTS (39% vs. 23%, p 0.03), and autonomic symptoms (59% vs. 9%, p < 0.01), compared to patients with CIAP who were not tested." (PMID 37266816, 2023). "The investigation of sciatic nerves was limited to the right thigh, without separate evaluation of tibial and peroneal divisions, although TTR polyneuropathy is a symmetric neuropathy involving both legs." (PMID 37329346, 2023). "The diagnosis of a pathogenic variant prompts early identification of possible affected relatives (familial screening), allowing the use of specific TTR targeted therapies, especially in the presence of polyneuropathy." (PMID 38275387, 2023). "Data from 397 patients affected by polyneuropathy of undetermined etiology who underwent TTR genotyping were initially considered for study inclusion in the study period." (PMID 37239276, 2023). "We carried out a retrospective cohort study to assess the yield of TTR gene sequencing in patients with polyneuropathy and assessed if the identified patients with ATTRv-PN had a clinical presentation typical of CIAP." (PMID 37266816, 2023). "Tafamidis, a TTR tetramer stabilizer approved to treat adult hATTR patients with stage 1 polyneuropathy, is widely used for patients with hereditary or wild-type ATTR with cardiomyopathy." (PMID 36829087, 2023). "From the 150 patients treated with TTR stabilizer, 84 remained stable, while in other 66 patients the treatment was terminated either because of polyneuropathy progression or due to death." (PMID 35463150, 2022). "The TTR polyneuropathy model was used to detect the sciatic nerve deposition of the aggregated mutated recombinant V30M TTR protein with fluorescence imaging." (PMID 36290413, 2022). "In particular, patisiran, a small interfering RNA acting as a TTR silencer, approved in Italy in 2020, has been shown to stabilize the course of polyneuropathy in ATTRv, but its administration is bound to the presence of neuropathy as a manifestation." (PMID 36672570, 2022). "The initial therapeutic success of tafamidis-based TTR tetramer stabilization for the treatment of ATTRv polyneuropathy prompted further clinical development of this drug to treat ATTR cardiomyopathy." (PMID 36555787, 2022). "Patisiran and Inotersen are silencers of TTR mRNA that have been approved by FDA for TTR polyneuropathy." (PMID 35337074, 2022). "Rats from the TTR polyneuropathy model were tested 10 days post-operation for mechanical allodynia using the Von Frey paw withdrawal test." (PMID 36290413, 2022). "Regarding TTR, compelling evidence for its amyloid seeding effects came from the observation of patients with hATTRV30M polyneuropathy who had undergone liver transplantation and subsequently developed cardiac deposition of WT TTR." (PMID 35393947, 2022). "The liver is indeed the main source of circulating transthyretin, and accumulation of the mutant protein in peripheral nerves forms amyloid deposits leading to rapidly progressing polyneuropathy." (PMID 33750896, 2021).
polyneuropathy (continued). "The percentage of patients receiving treatment has increased considerably, owing to the availability of tafamidis, approved by the EMA in November 2011 for adult patients with transthyretin-related polyneuropathy." (PMID 33925301, 2021). "It is the second of two small molecules investigated in animal safety studies and human clinical trials for the treatment of transthyretin (TTR) polyneuropathy." (PMID 34772213, 2021). "With respect to new therapeutic approaches, we strongly propose genetic testing of the TTR gene in an extended cohort of patients with unexplained heart failure and progressive polyneuropathy." (PMID 32674397, 2020). "This system can bring more objectivity to motor function assessment of polyneuropathy patients, potentially contributing to an improvement of TTR-FAP treatment and understanding, with great benefits to the patients’ quality of life." (PMID 31726742, 2019). "As a result, amyloid fibrils accumulate and cause function impairment of different organs and tissues, particularly in the peripheral nerves leading to polyneuropathy (TTR‐FAP)." (PMID 29568686, 2018). "These discriminators were validated comparing TTR‐FAP patients with a cohort of patients with chemotherapy‐induced polyneuropathy (CIN) and chronic inflammatory demyelinating neuropathy (CIDP)." (PMID 29568686, 2018). "In 2011, the drug tafamidis, a compound with high ability to bind and stabilize the tetrameric fold of TTR, was approved by the European Medical Agency for treatment of TTR-related hereditary amyloidosis patients with stage I polyneuropathy." (PMID 27050398, 2016). "Pharmacological stabilization of the protein TTR and amyloid fibril disruptors are being developed for polyneuropathy." (PMID 26664897, 2015). "The unconjugated ASOs are currently in late stage clinical trials for the treatment of familial chylomicronemia and TTR-mediated polyneuropathy." (PMID 24992960, 2014). "In the polyneuropathy study, 21 patients with non-Val30Met TTR-FAP received tafamidis for 12 months, with TTR stabilization at week 6 compared with baseline as the primary outcome measure." (PMID 23425518, 2013). "Familial amyloidosis with polyneuropathy (FAP) is an autosomal dominant disease caused by transthyretin (TTR) mutations, of which V30M (TTR c.148G > A, p.Val50Met, "Val30Met") is the most common." (PMID 20840742, 2010). "Clinicians should perform the TTR genetic analysis in patients with neuronopathic-like polyneuropathy, while in patients with other type of polyneuropathy, they have to look for ATTRv multisystemic involvement (red flags) in order to suspect ATTRv disease and thus perform an early diagnosis." (PMID 37870643, 2024). "This trial involved patients suffering from TTR-Mediated-Polyneuropathy." (PMID 39684857, 2024). "Out of 338 patients with polyneuropathy, 10 patients had a pathogenic TTR gene mutation (all p.Val50Met) and none had a clinical presentation typical of CIAP." (PMID 37266816, 2023). "Transthyretin amyloidosis (ATTR amyloidosis) is a multisystemic, life-threatening disease resulting from the deposition of transthyretin (TTR) amyloid fibrils in the heart, peripheral nerves, and other tissues, leading mainly to polyneuropathy and/or cardiomyopathy." (PMID 35717381, 2022). "ASO-mediated degradation occurs via the enzyme RNase H. The ASO therapy Inotersen, like Patisiran, binds to both wild-type and mutant TTR, induces a measurable decrease in mutant TTR level, and also received FDA-approval for the treatment of hATTR-associated polyneuropathy." (PMID 36341129, 2022). "Two other agents, inotersen (an antisense oligonucleotide) and patisiran (a micro-ribonucleic acid inhibitor) are injectable therapies classified as TTR gene silencers that are approved for the treatment of ATTRh polyneuropathy only, and act by reducing hepatic TTR production." (PMID 35656395, 2022).
polyneuropathy (continued). "Misfolding of mutant TTR promotes the accumulation of insoluble protein fibers, which are deposited predominantly in heart and nervous tissue, leading to cardiomyopathies and polyneuropathies." (PMID 34539755, 2021). "A population-based genome-first approach for identification of P/LP TTR gene variants has the potential to diagnose cases of previously unrecognized ATTR and identify patients at risk for developing hATTR cardiomyopathy or polyneuropathy." (PMID 34746851, 2021). "Of interest, in the clinical trial investigating the therapeutic effect of patisiran in patients with hereditary ATTR amyloidosis with polyneuropathy, a correlation between the degree of the reduction in TTR levels from baseline and neurological manifestations was observed." (PMID 32754033, 2020). "In two patients with late onset hypertrophic cardiomyopathy and mild polyneuropathy at 74 and 81 years due to ATTR amyloidosis, two rare TTR variants (c.-61G>A; p.Arg5Cys) of unknown significance (VUS) were identified." (PMID 32674397, 2020). "The nanobody B10AP grafted with Gd(DOTA) shows detection towards amyloid fibers of islet amyloid polypeptide (IAPP) and fibers of transthyretin (TTR), which are involved in type 2 diabetes and polyneuropathy, respectively, and has great affinities with KD values in the 10-nM range in vitro." (PMID 30231587, 2018). "We want to stress that a careful and comprehensive clinical neurological examination is essential in the work‐up of polyneuropathies, but that these three parameters should be paid special attention to, in order to discriminate TTR‐FAP from other polyneuropathies." (PMID 29568686, 2018). "Taken together, these results suggest that MMP-14 might be a potential disease and therapeutic biomarker in TTR polyneuropathy." (PMID 28993312, 2017). "Some adult patients with diabetes mellitus may develop a polyneuropathy similar to TTR-FAP with early and predominant small-fiber involvement and autonomic dysfunction." (PMID 23425518, 2013). "The therapeutic effect of TTR tetramer stabilization with tafamidis meglumine was first evaluated in the context of a multi-center, international, randomized, double-blind, placebo-controlled clinical trial on early-stage ATTRv polyneuropathy, recruiting 125 patients." (PMID 36555787, 2022). "Three patients without a TTR mutation and one of the two patients with V122I mutation reported a prior diagnosis of neuropathy, although they denied the typical sensory symptoms of polyneuropathy." (PMID 35959393, 2022). "Furthermore, therapeutic small RNA drugs are becoming novel promising therapeutics since the first small-interfering RNA (siRNA) drug, Patisiran, which acts by binding and degrading transthyretin mRNA, was approved for the treatment of a rare polyneuropathy by FDA in 2018." (PMID 32547948, 2020). "Therefore, we investigated the yield of TTR gene sequencing in a Dutch population of patients with polyneuropathy, assessed if the identified patients with ATTRv-PN could have been misdiagnosed as CIAP, and which are potentially the most outstanding and differentiating clinical features." (PMID 37266816, 2023). "Alternative treatments for TTR, the TTR silencers patisiran and inotersen received regulatory approval for hereditary ATTR polyneuropathy in late 2010s and are undergoing clinical trials for ATTR cardiomyopathy." (PMID 35810311, 2022). "The first siRNA drug Onpattro (patisiran) targeting transthyretin (TTR) has been approved by the U.S. Food and Drug Administration (FDA) in 2018, for the treatment of peripheral nerve disease polyneuropathy in adults." (PMID 31744202, 2019). "In Canada, these include the use of TTR protein stabilizers, which are currently indicated to treat ATTR cardiomyopathy, and the use of TTR gene silencers, which are currently indicated to treat ATTRv polyneuropathy." (PMID 40433205, 2025).
polyneuropathy (continued). "This potential drug was tested in 6 patients with hATTR and polyneuropathy with and without TTR-cardiomyopathy and showed a significant reduction of TTR-levels." (PMID 38809394, 2024). "TTR-stabilizers (tafamidis and diflunisal) have been studied and used for over a decade and have proven to retard disease progression and improve outcomes in patients with ATTR-CM and polyneuropathy." (PMID 37843599, 2024). "There is an ongoing debate on the non-specificity of RAGE binding across many neurologic disorders and different forms of amyloid fibrils, and it is still not clear from the literature if this is TTR polyneuropathy-specific." (PMID 37830598, 2023). "In this phase I clinical trial, six hATTR patients with polyneuropathy received NTLA-2001 injection, and 28 days later, circulating TTR levels were reduced in a dose-dependent manner, with an average of 52 and 87% TTR reduction in the lower-dose group and the higher-dose group, respectively." (PMID 38020120, 2023). "In a recent open label study of six patients with ATTR and polyneuropathy, lipid nanoparticle (intravenous delivery) of mRNA for Cas9 protein and a single-guide RNA targeting TTR led to a dose-dependent reduction in TTR of up to 87% at the highest dose." (PMID 35596796, 2022). "Low ulnar SNCV, impaired cold perception, and mechanical hyperalgesia at the hands seem to characterize TTR‐FAP and might help to differentiate from other polyneuropathies." (PMID 29568686, 2018). "We looked for a “signature” of TTR‐FAP and applied a battery of clinical and electrophysiological tests to characterize TTR‐FAP and compared these results to patients with common types of polyneuropathy." (PMID 29568686, 2018). "The subject bearing the mutation A108V in heterozygoty presented a mild, non-progressive, sensory neuropathy without any dysautonomic symptom or sign, a course that is not typical of a TTR-related polyneuropathy." (PMID 28338000, 2017). "Orthotopic liver transplantation (OLT), which replaces the source of mutant TTR, has been mainly used in patients with early-stage polyneuropathy without cardiac involvement; however, this strategy has been utilized much less in recent years after the introduction of medical therapy." (PMID 32641071, 2020). "MRI biomarkers correlated with previously validated clinical outcome measures, Polyneuropathy Disability scoring system, Neuropathy Impairment Score (NIS) and NIS-lower limb, and neurophysiological parameters of axonal damage regardless of age, sex, treatment and TTR mutation." (PMID 36064814, 2023). "For the TTR-FAP group, mean CSAs at each site were not correlated with different Coutinho stages, modified polyneuropathy disability, course of sensory motor peripheral neuropathy, Neuropathy Impairment Score, or Norfolk Quality of life-diabetic neuropathy score." (PMID 33716932, 2021).